LEPR (leptin receptor)
Diseases named in the same sentence as LEPR in open-access papers (continued):
Sharing a sentence is not in itself a finding about the gene and the disease.
Obesity (continued). "The most common monogenic form of obesity is associated with mutations in the MC4R gene, followed by mutations in the LEPR, POMC, PCSK1, and LEP genes." (PMID 39777073, 2024). "Disruption of the hypothalamic circuits controlling body weight and appetite caused by mutations in the genes encoding leptin, LEPR, POMC and MC4R can lead to severe obesity in humans." (PMID 39526054, 2024). "Previous studies have established a significant association between several genes and obesity, such as the fat mass and obesity-associated (FTO) gene, melanocortin-4 receptor (MC4R) gene, and leptin receptor (LEPR) gene." (PMID 38674446, 2024). "Diabetes (db) mutation in LepR gene was first found in C57BL/KsJ strain, with homozygous mice showing severe DM signs with early disease onset, obesity by 3–4 weeks and subsequent hyperglycemia, glycosuria, polyuria, and retinal ganglion cell death." (PMID 37887287, 2023). "In patients with other rare genetic diseases of obesity, such as POMC, proprotein convertase subtilisin/kexin type 1 (PCSK1), or LEPR deficiency, notable impairments in quality of life have been reported." (PMID 36647077, 2023). "Collectively, these results indicate that LAT1 depletion in LepR-expressing neurons leads to spontaneous obesity owing to an increase in fat mass, concomitant with reduction in BCAA uptake in the VMH." (PMID 36862514, 2023). "[125I]IMT uptake was significantly decreased in the hypothalamus of LepR-Cre Slc7a5fl/fl mice before the onset of obesity (7 weeks of age)." (PMID 36862514, 2023). "On the other hand, reduced expression of Pomc and Ucp2 as well as hyperphagia would predict, together with the slight decrease in leptin receptor expression, a positive energy balance and obesity, possibly due to partial leptin resistance." (PMID 36581316, 2023). "The genetic screening of 454 families from our cohort, with severe obesity, identified 132 probands (29%) and 13 family members with homozygous or compound heterozygous (likely) pathogenic variants in LEP, LEPR, or MC4R." (PMID 37659411, 2023). "Serum leptin levels were significantly increased in LepR-Cre Slc7a5fl/fl mice prior to the onset of obesity (7 weeks of age) and after the diagnosis of obesity (24 weeks of age)." (PMID 36862514, 2023). "Here, we present a retrospective clinical history of 92 children suffering from severe obesity due to LEP and 32 cases with LEPR deficiency, all from a single geographical region of Punjab, Pakistan." (PMID 37659411, 2023). "Leptin is a cytokine: what are the roles of LepR in microglia or astroglia to aid and abet obesity-induced hypothalamic inflammation?" (PMID 36769012, 2023). "Disrupted GABA release from LepR-expressing neurons has been shown to contribute to mild obesity and sensitivity to diet-induced obesity in mice." (PMID 37550777, 2023). "In both models, the leptin receptor pathway is affected, leading to hyperphagia, massive obesity, and fat mass gain." (PMID 37650104, 2023). "Strong leptin receptor expression and the manifestation of overweight and obesity are factors influencing the occurrence of excessive leptin concentrations." (PMID 36981858, 2023). "It has been found that HFD-induced obesity stimulated Mmp-2 protein activation within the hypothalamus with subsequent cleavage of the extracellular domain of the leptin receptor." (PMID 38068822, 2023). "It is an MC4 receptor agonist developed for the treatment of obesity arising from POMC, proprotein convertase subtilisin/kexin type 1 (PCSK1), or LEPR deficiency." (PMID 37712012, 2023). "Highly infrequent single gene mutations (such as LEP, LEPR and POMC) stand for rare cases of monogenic obesity; however, some of them are also related to polygenic obesity (such as MC4R and FTO)." (PMID 36980866, 2023). "In this context, polymorphisms in the LEPR and FTO genes have been associated with GWG, at least in adult women, particularly in those beginning pregnancy with overweight or obesity." (PMID 36986260, 2023).
Obesity (continued). "Setmelanotide is an effective medication for the disease of obesity in patients older than 6 years if the patient has POMC deficiency, PCSK1 deficiency, LEPR deficiency, or Bardet–Biedl syndrome." (PMID 37835041, 2023). "Leptin positively regulates these SNS neurons through MBH-localized AgRP/NPY-, POMC/CART-, and SH2B-expressing neurons since deletion of LepR in those neurons results in obesity with the inefficiency of thermogenesis and lipolysis." (PMID 37547309, 2023). "In contrast, AgRP-specific leptin receptor deletion in adult animals leads to massive obesity, reproducing the phenotype of db/db mice." (PMID 37887286, 2023). "Male and female T cell-specific leptin receptor knockout mice and littermate controls were placed on low-fat diet or high-fat diet to induce obesity for 18 weeks." (PMID 37276236, 2023). "The db/db mouse has a mutant leptin receptor which results in impaired satiety, hyperphagia and obesity which is commonly used to study T2DM and its complications." (PMID 37731032, 2023). "We found that the LepR in AgRP neurons plays a pivotal role in the control of obesity and glucose homeostasis." (PMID 37043384, 2023). "The genetically induced hyperphagia and obesity in leptin- and leptin receptor-knockout mice, as well as in Zucker obese rats, are associated with the development of insulin resistance, T2DM, and abnormal leptin signaling." (PMID 36674935, 2023). "In a Turkish study of 105 children with early-onset obesity that screened 41 monogenic obesity genes, around 10.5% of the cases were found to carry genetic variants in the SIM1, POMC, PSCK1, MC4R, and LEPR genes." (PMID 37329217, 2023). "For example, setmelanotide, a MC4R agonist is FDA approved for treatment of monogenic obesity related to POMC deficiency, leptin receptor (LEPR) deficiency, and Bardet Biedl syndrome." (PMID 37780616, 2023). "It was found that hesperidin binds to leptin receptor with high affinity and causes a favourable geometric conformation change of leptin receptor, promoting its binding to leptin, which may lead to the final lipolysis and fat cascade, and may eventually lead to the treatment of obesity." (PMID 37036026, 2023). "Epinephrine and norepinephrine levels were significantly lower in the serum and urine of LepR-Cre Slc7a5fl/fl mice than in control mice before the onset of obesity (7 weeks of age) and after the diagnosis of obesity (24 weeks of age)." (PMID 36862514, 2023). "Leptin and leptin receptor are well-documented mediators of obesity through their role in appetite suppression; however, their potential role in FMC was only recently explored." (PMID 37626804, 2023). "A study that evaluated FABP2, LEPR, LEP and FTO polymorphisms in individuals who underwent RYGB found that the %EWL was higher in patients with obesity carriers of the LEP variant rs1137101, 12 and 24 months after surgery." (PMID 37129798, 2023). "Setmelanotide was initially FDA-approved in 2020 for chronic weight management in individuals six years or older with obesity caused by POMC deficiency, proprotein subtilisin/kexin type 1 (PCSK1), or LEPR deficiency." (PMID 37937009, 2023). "The function of leptin receptor signaling in obesity pathogenesis has been well reported, in part supported by the striking metabolic phenotype exhibited by the db/db mouse which carries Lepr mutation." (PMID 36707678, 2023). "During obesity, leptin resistance occurs due to leptin’s inability to reach the target cells, reduced LepR gene expression or disturbed LepR signaling." (PMID 38136564, 2023). "Using our T cell-specific leptin receptor conditional knockout mouse, we interrogated the role of leptin signaling on the pathogenesis of obesity as driven by the T cell." (PMID 37276236, 2023). "The obesity, fat accumulation, and insulin insensitivity in LepR-Cre Slc7a5fl/fl mice were ameliorated in LepR-Cre Slc7a5fl/fl Tsc1fl/+ mice." (PMID 36862514, 2023).
Obesity (continued). "The knockout of leptin receptor in the CNS neurons leads to severe obesity, hyperinsulinemia, hyperglycemia and hepatic steatosis in male mice." (PMID 37013864, 2022). "It is interesting to see that genetic variants in LEPR gene, as occurs in the ZFR murine model, can cause obesity, hypercholesterolemia, hyperinsulinemia, hyperlipidemia and also ossification of spinal ligaments, similar to human OPLL." (PMID 36276944, 2022). "We assessed the expression of Mfn1 and 2 in islets isolated from the leptin receptor deficient db/db BKS mouse model, which develops obesity, progressive β-cell mitochondrial and insulin secretory dysfunction, and eventual β-cell failure." (PMID 35487893, 2022). "The US Food and Drug Administration approved the drug for chronic weight management in patients 6 years and older with obesity caused by POMC, PCSK1, and LEPR deficiency." (PMID 36232301, 2022). "The FDA approved setmelanotide in November 2020 for the treatment of obesity in patients with POMC, PCSK1 or LEPR deficiency." (PMID 34815532, 2022). "In this sense, different studies have analyzed leptin levels and leptin/leptin receptor expressions as a probable bridge between obesity and lymphomas." (PMID 36555171, 2022). "Several polymorphisms in humans that are attributed to an obesity phenotype have been identified in the LEP and LEPR genes: an A to G nucleotide change at position 19 in the 5 V-untranslated region." (PMID 35886710, 2022). "One is the db/db mouse that develops a diabetes with obesity, due to a deficit in the expression of leptin receptor, which leads to obesity and type II Diabetes." (PMID 36225882, 2022). "Genetic correlations between the SNPs used to create the LepR-ePRS and several GWASes related to lipid metabolism and obesity were found in LD-hub using the PFC scores." (PMID 36241774, 2022). "Using CRISPR‐Cas9 technology, Bao and colleagues established LepR knockout rats, which ultimately exhibited complications of obesity and diabetes." (PMID 35845351, 2022). "Genetic disruptions of the LepR have been observed in inherited obesity, and it appears to be the most likely reason for the development of human obesity." (PMID 35886710, 2022). "Setmelanotide (Imcivree) is a melanocortin-4 (MC4) receptor agonist used for the treatment of obesity due to proopiomelanocortin (POMC), proprotein convertase subtilisin/keying type 1 (PCSK1), or leptin receptor (LEPR) deficiency." (PMID 36232301, 2022). "Studies have shown that significant hyperinsulinemia have occurred in leptin receptor knockout mice, confirming that leptin receptor pathway plays a crucial role in obesity-induced hyperinsulinemia." (PMID 35198097, 2022). "The baseline characteristics of patients who enrolled in these two Phase 3 trials suggest that individuals living with rare genetic diseases of obesity, such as POMC or LEPR deficiency, have an impaired, and in some cases severely impaired, QOL." (PMID 35123544, 2022). "Leptin is overexpressed in adipose tissue in cases of obesity, as well as due to resistance mechanisms leading to leptin’s inability to reach targeted cells, decreased leptin receptor (LEPR) expression, or altered signaling." (PMID 35563103, 2022). "This synthetic peptide was approved by FDA at the end of 2020 for treating obesity caused by genetic defects in pro-opiomelanocortin (POMC), leptin receptor (LEPR), or proprotein convertase subtilisin/kexin type 1 (PCSK1)." (PMID 36291616, 2022). "The present work, therefore, focuses on the evaluation of the association of clinical markers related to obesity and SNPs of the LEP, LEPR, POMC, PCSK1, and MC4R genes in a healthy Mexican population." (PMID 35741707, 2022). "Of several variants in LEP, LEPR, and FTO genes identified and tested for obesity association, only a few have been successfully replicated in different world populations." (PMID 36126070, 2022).
Obesity (continued). "Structural variants of genes associated with BC and obesity, including LEP, LEPR, PON1, FTO, and MC4R, are associated with a higher or lower risk of BC." (PMID 36253742, 2022). "The leptin receptor (LepR) acts as a signaling nexus for the regulation of glucose uptake and obesity, among other metabolic responses." (PMID 35159237, 2022). "Setmelanotide was first approved in November 2020 by the U.S. FDA (USA) and is a novel medication for treating obesity caused by POMC and LEPR deficiency." (PMID 36009013, 2022). "Overall, we report six genetic variants of ADIPOQ, FTO and LEPR genes as obesity-risk markers and a CETP gene variant as lean mass/obesity protective marker in studied Pakistani cohort." (PMID 36126070, 2022). "At the limits, this is exemplified by the ob/ob and db/db mice that lack leptin and the long form of the LEPR, respectively, and have elevated food intake, suppressed metabolism, and enormous obesity." (PMID 36394061, 2022). "For the genes NRF1, FTO, and LEPR, our study demonstrates a race-specific difference in the DNA methylation of these obesity-related genes." (PMID 36360268, 2022). "The Lepr−/− rat is a newly developed leptin receptor knockout rat model characterized by obesity, glucose intolerance, and dyslipidemia, which is proven to be a suitable animal model to study obesity complication." (PMID 36230016, 2022). "Together, hyperphagia, the accompanying obesity, and associated comorbidities can contribute to physiologic and psychological impairments and reduced QOL in patients with POMC or LEPR deficiency." (PMID 35123544, 2022). "Two obesity mice models were performed, one using 12 weeks of the dietary protocol with a high-fat (HF) diet in C57BL/6 mice and the other using leptin receptor-deficient mice (db/db-/-), which became spontaneously obese." (PMID 36417595, 2022). "To date, the influence of leptin and leptin receptor expression and regulation has been centered around obesity." (PMID 35628271, 2022). "BMI in our studied population showed a direct relationship with the transcriptional changes (downregulated) observed on selected genes (APC, ARNT, CYP2D6, LEPR, LRP12, and MYC), all of which are closely linked to the development of cancer or obesity." (PMID 35420343, 2022). "Regarding the relationship of obesity with CRC, LEP polymorphisms such as rs7799039 and LEPR rs1137101 were shown to be associated with CRC risk, with specific alleles or genotypes linked to increased obesity risk." (PMID 35563103, 2022). "Obesity is linked to the expression, rare mutations, and polymorphic profiles of LEP and LEPR genes, as well as epigenetic events and other genes involved in energy regulation and metabolism." (PMID 35563103, 2022). "In the same study, the gene variant of the leptin receptor, LEPR Q223, had demonstrated positive correlation with obesity risk, similar to the leptin gene (LEP −2548 AA)." (PMID 36551995, 2022). "The BMI increasing alleles of FTO, LEPR and ADIPOQ genetic variants are common in Pakistani individuals thus increasing their risk towards obesity." (PMID 36126070, 2022). "In the attempt to identify obesity-driven tumour susceptibility pathways that might alter energy balance, leptin–LEPR signalling has been a focus of cancers of which the normal stem cells express LEPR and exist in a fatty tissue microenvironment in which local leptin is high." (PMID 36450983, 2022). "In the next section, the main LEP and LEPR gene mutations associated with obesity and CRC are described to review their impact and potential link with obesity and CRC." (PMID 35563103, 2022). "Leptin resistance has been demonstrated in obesity states as a reactive increase due to leptin receptor downregulation." (PMID 35242246, 2022). "The recessive mutant gene “fatty” (fa) of the leptin receptor is the reason for the impaired leptin signaling and extreme obesity with juvenile onset." (PMID 35589696, 2022).
Obesity (continued). "Morbid early childhood obesity with normal development suggests leptin pathway gene mutation (LEP, LEPR, and PCSK1 mutations), if delayed development consider Prader-Willi syndrome or Bardet-Biedl syndrome." (PMID 35530907, 2022). "Leptin-receptor mutant db/db mice exhibit many of the clinical characteristics of type 2 diabetes and metabolic syndrome, including hyperglycemia, hyperinsulinemia, obesity, hypertension, hyperlipidemia, and glucose intolerance." (PMID 35310970, 2022). "Other genes that can predispose individuals to obesity include the fat mass and obesity-associated (FTO) gene, leptin receptor (LEPR), and melanocortin-4 receptor (MCR4)." (PMID 36012526, 2022). "Additional clinically relevant variants or CNVs in genes related to obesity, such as MC4R, POMC and LEPR, were excluded by exome sequencing and a TruSight One Sequencing panel." (PMID 36536132, 2022). "In particular, genome-wide association studies have investigated the influence of specific genetic loci in the pathophysiology of obesity, identifying different LEP and LEPR polymorphisms and measuring their impacts on adiposity development." (PMID 34208585, 2021). "We next analyzed two genetic models of obesity: leptin gene mutant (ob/ob) mice and leptin receptor mutant (db/db) mice." (PMID 35011234, 2021). "On the other hand, the genetic variants associated with adipogenesis and inflammation to increase insulin resistance, including fat mass and obesity-associated (FTO)_rs1421085, leptin receptor (LEPR)_rs1137100, and PPARγ_rs1801282, are also reported." (PMID 34834527, 2021). "A model of type 2 diabetes mellitus, called db/db mice, is characterized by a deletion of the leptin receptor gene; this deficit leads to obesity, insulin resistance, and type 2 diabetes mellitus." (PMID 34685538, 2021). "After the first reports on humans with early-onset severe obesity carrying biallelic likely pathogenic variants in the leptin (LEP) and leptin receptor gene (LEPR), it was clear that a fundamental failure in LEP and LEPR signaling causes a dramatic phenotype." (PMID 34448070, 2021). "Initially, we started by testing GPS18169 in a genetic model of obesity (fa/fa rats) related to a defect in the leptin receptor." (PMID 33673598, 2021). "measured miRNAs in whole breast milk that target mRNA of leptin (LEP), adiponectin (ADIPOQ) and their respective receptors (LEPR, ADIPOR1 and ADIPOR2) which are associated with obesity." (PMID 33801634, 2021). "These include mutations in leptin and its receptor (LEPR), prohormone convertase 1 (PC1), and fat mass and obesity associated (FTO) gene." (PMID 34777390, 2021). "In the present study, naturally developed DN in mice with genetic defects in the leptin receptor (db/db) is a well-established model for type 2 diabetes, obesity and insulin resistance." (PMID 33779731, 2021). "Molecular analysis of the brain in the same model, in addition to HFD-fed mice, showed that obesity rapidly increases LepR expression in astrocytes where it then influences the leptin-induced calcium signaling in astrocytes." (PMID 34201099, 2021). "Recent work has further characterized this population into, roughly, 2 distinct subtypes: leptin receptor+ (LepR+) cells, which are relevant to obesity, and the Ng2+ population." (PMID 33554957, 2021). "Since our experiment was performed on Zucker rats with obesity induced by a mutation in the leptin receptor, we suggest that the body mass reduction obtained by IT procedure was substantial enough to lower RBP4 levels in animals with endogenous obesity." (PMID 33833309, 2021). "In accordance with the pleiotropic actions of leptin, emerging studies have evaluated the efficacy of leptin-based and LEPR antagonist therapy as anti-obesity approaches in the setting of both leptin sensitivity and resistance states." (PMID 34208585, 2021).